PRRT2 (proline rich transmembrane protein 2)
Diseases named in the same sentence as PRRT2 in open-access papers (continued):
Sharing a sentence is not in itself a finding about the gene and the disease.
epilepsy (continued). "A single case of a contiguous gene deletion (578 kb, 16p11.2) involving the PRRT2 gene was identified with an extended phenotype including psychomotor retardation, hemiplegic migraine, epilepsy, myoclonus, and dystonia." (PMID 29352095, 2018). "Mutations in the proline-rich transmembrane protein 2 (PRRT2) gene cause a wide spectrum of neurological diseases, ranging from paroxysmal kinesigenic dyskinesia (PKD) to mental retardation and epilepsy." (PMID 27172900, 2016). "Proline-rich transmembrane protein 2 (PRRT2) has been identified as the single causative gene for a group of paroxysmal syndromes of infancy, including epilepsy, paroxysmal movement disorders, and migraine." (PMID 26797119, 2016). "Homozygous PRRT2 mutations were associated with clinical features also observed in a subset of individuals with ASD such as intellectual disability and epilepsy." (PMID 24594579, 2014). "We explore the phenotypic spectrum of PRRT2-related epilepsy through international collaboration." (PMID 40401013, 2025). "Monogenic epilepsies can be characterized according to the gene function affected: Impaired function of ion channels (e.g., CACNA1A), receptors (e.g., GABRB3), transporters (e.g., SLC2A1), synapse-related (e.g., PRRT2), and other pathways (e.g., CDKL5, PCDH19) are associated with epilepsy." (PMID 38125836, 2023). "A rare frameshift variant in brain-expressed PRRT2 confers large risk of MA and epilepsy, but not MO." (PMID 37884687, 2023). "Therefore, in clinical cases of repeated brief afebrile bilateral tonic–clonic seizures at initial onset, PRRT2‐related epilepsy should be considered, and SCBs should be used for seizure control." (PMID 36775847, 2023). "Although these atypical cases could not be classified as SeLIE, they will contribute to the complete understanding of the clinical spectrum of PRRT2‐related epilepsy." (PMID 36775847, 2023). "To validate our bioinformatic prediction, we aimed to determine whether PRRT2 can physically interact with proteins in the dysregulated epilepsy subnetwork." (PMID 36808153, 2023). "Furthermore, we suggest the administration of SCB for patients with a distinct phenotype of PRRT2‐related epilepsy at the initial presentation." (PMID 36775847, 2023). "It is indicated that VPA has a good therapeutic effect on PRRT2-related epilepsy." (PMID 37880614, 2023). "The peak age of seizure onset in PRRT2‐related epilepsy is three to 9 months." (PMID 36775847, 2023). "In addition, six atypical cases with neonatal‐onset seizures and unremitting after 3 years of age were included to understand the expanded clinical spectrum of PRRT2‐related epilepsy." (PMID 36775847, 2023). "Together this data suggests that PRRT2 may interact with the epilepsy subnetwork and impact downstream disease processes in 16p11.2dup/+ mice." (PMID 36808153, 2023). "PRRT2-related epilepsy is a self-limited epilepsy that may be accompanied by various EEG abnormalities." (PMID 37880614, 2023). "However, these genes are known to be different in the peak onset of seizures from PRRT2‐related epilepsy, and little is known about the electroclinical features when the seizure onset of patients with pathogenic variants in these genes overlaps with SeLIE." (PMID 36775847, 2023). "Further, we examined whether the PRRT2 interactome could directly interact with proteins in the epilepsy subnetwork identified in 16p11.2dup/+ mice." (PMID 36808153, 2023). "By comparison, the response to LEV was inferior in PRRT2- and KCNQ2-related epilepsy, and it may probably be useful for SCN1A-associated epilepsy." (PMID 35720076, 2022). "Thirty-five patients manifested epilepsy without any other comorbidity and seven of them (20.0%) carried variants in six genes, namely KCNQ2, NALCN, PAK3, PRRT2, SCN1A, and SLC2A1 that are among the well-known genes causing epilepsies or syndromes including epilepsy." (PMID 36035117, 2022).
epilepsy (continued). "Although epilepsy caused by the KCNQ2, KCNQ3, PRRT2, SCN2A and SCN8A gene are relatively benign, in our study, more than 18 genes caused epilepsy accompanied by the intellectual disability and more than 14 genes caused syndromes with epilepsy." (PMID 35571021, 2022). "Despite HM being the commonest reported phenotype, PRRT2 mutations can also manifest with other, non-complicated, types of migraine, with or without aura, generally associated with epilepsy and/or PKD." (PMID 33746883, 2021). "It is therefore plausible that the occurrence of febrile seizures in patients with a PRRT2 gene mutation is not solely caused by this mutation, but by the occurrence of epilepsy itself." (PMID 24370076, 2013). "The results clearly demonstrate that pHIL is highly effective in suppressing or greatly weakening the epileptic paroxysms in adult PRRT2 KO mice and suggest that it could be a seizure-preventive treatment in chronic epilepsy forms in which seizures are triggered by sensory stimuli." (PMID 38965228, 2024). "By performing network analysis, we found that PRRT2 had the highest degree of connectivity (D = 16) and betweenness centrality (CB = 0.37) in this network, making it the most topologically important node, and central hub in the epilepsy subnetwork of 16p11.2dup/+ mice." (PMID 36808153, 2023). "Thus, our data strongly implicates hub protein PRRT2 as a regulator of the epilepsy subnetwork disrupted in 16p11.2dup/+ mice, and suggests it may impact core disease phenotypes." (PMID 36808153, 2023). "Although the brain area where PRRT2 is mostly enriched is the cerebellum, ataxia represents the least common phenotype in humans, raising the question of whether or not dysfunction of cerebellar activity is involved also in the genesis of PxD and epilepsy." (PMID 33746883, 2021). "Eighty-one epilepsy-related genes were detected; the gene most frequently detected was KCNQ2 (nine times), followed by PRRT2 (seven times), SCN1A (six times), SCN2A (five times), SPTAN1 (four times), and TSC2 (four times)." (PMID 35571021, 2022). "Intriguingly, loss-of-function mutations in PRRT2 (as opposed to gain-of-function in the duplication) cause benign familial infantile seizures (OMIM: 605751), one of the most common infantile seizure disorders." (PMID 36808153, 2023).
paroxysmal kinesigenic dyskinesia (63 papers, 2012 to 2026). "Proline-rich transmembrane protein 2 (PRRT2) plays a pivotal role in the control of voluntary movements, as PRRT2 mutations cause paroxysmal kinesigenic dyskinesia (PKD) in a loss-of-function manner." (PMID 42243635, 2026). "The PRRT2 mutations would lead to paroxysmal kinesigenic dyskinesia (PKD) and paroxysmal hypnogenic dyskinesia (PHD) in adults and self-limited familial neonatal-infantile epilepsy or infantile convulsion and choreoathetosis (ICCA) in infants." (PMID 39039444, 2024). "Lamotrigine has been reported to be effective in patients with paroxysmal kinesigenic dyskinesia caused by the PRRT2 gene." (PMID 36775847, 2023). "Accordingly, PRRT2 loss-of-function mutations associate with pleiotropic paroxysmal neurological disorders, including paroxysmal kinesigenic dyskinesia, episodic ataxia, benign familial infantile seizures, and hemiplegic migraine." (PMID 36441479, 2023). "The other three patients did not undergo brain MRI because of a definite family history of SeLIE or paroxysmal kinesigenic dyskinesia and genetic confirmation of pathogenic variants of the PRRT2 gene." (PMID 36775847, 2023). "In paroxysmal kinesigenic dyskinesia patients with a PRRT2 gene mutation, decreased FC within a DMN was found." (PMID 36669351, 2023). "The exception was a girl whose family members (father and older brother) were diagnosed with SeLIE and paroxysmal kinesigenic dyskinesia caused by a PRRT2 variant and whose parents wanted to prevent the recurrence of seizures until self‐remission." (PMID 36775847, 2023). "Proline-rich transmembrane protein 2 (PRRT2) is a protein that is enriched in the brain and is associated with a group of paroxysmal disorders, such as paroxysmal kinesigenic dyskinesia." (PMID 35496318, 2022). "PRRT2 is a major causative gene for self-limited familial neonatal-infantile epilepsy, paroxysmal kinesigenic dyskinesia, and paroxysmal kinesigenic dyskinesia with infantile convulsions." (PMID 35959395, 2022). "PRRT2-associated diseases are mainly paroxysmal kinesigenic dyskinesia (PKD) and paroxysmal hypnogenic dyskinesia (PHD) in adults and self-limited familial neonatal-infantile epilepsy or infantile convulsion and choreoathetosis (ICCA) in infants." (PMID 35959395, 2022). "Paroxysmal kinesigenic dyskinesia is an episodic movement disorder caused by dominant mutations in the proline-rich transmembrane protein PRRT2, with onset in childhood and typically with improvement or resolution by middle age." (PMID 34101060, 2021). "Mutations in the PRRT2 gene are the main cause for a group of paroxysmal neurological diseases including paroxysmal kinesigenic dyskinesia, episodic ataxia, benign familial infantile seizures, and hemiplegic migraine." (PMID 34685646, 2021). "For example, paroxysmal kinesigenic dyskinesia is most commonly associated with variants in PRRT2 but also variants identified in PNKD, SCN8A, and SCL2A1." (PMID 34177764, 2021). "Mutations in PRoline Rich Transmembrane protein 2 (PRRT2) cause pleiotropic syndromes including benign infantile epilepsy, paroxysmal kinesigenic dyskinesia, episodic ataxia, that share the paroxysmal character of the clinical manifestations." (PMID 33731672, 2021). "Mutations in the PRRT2 gene cause a variety of paroxysmal disorders including paroxysmal kinesigenic dyskinesia (PKD), benign infantile epilepsy, episodic ataxia, and migraine that can be present alone or in combination." (PMID 33731672, 2021). "Mutations in the PRRT2 gene cause a broad spectrum of paroxysmal neurological diseases including paroxysmal kinesigenic dyskinesia, episodic ataxia, benign familial infantile seizures, and hemiplegic migraine." (PMID 34685646, 2021). "PRRT2 mutations are the major causative agent of paroxysmal kinesigenic dyskinesia with infantile convulsion (PKD/IC)." (PMID 32509037, 2020).
paroxysmal kinesigenic dyskinesia (continued). "Mutations in the proline-rich transmembrane protein 2 (PRRT2) gene cause a wide spectrum of neurological diseases, ranging from benign familial infantile epilepsy to paroxysmal kinesigenic dyskinesia and migraine." (PMID 31940887, 2020). "The objective of this study was to summarize clinical features and PRRT2 mutations of paediatric paroxysmal kinesigenic dyskinesia (PKD) patients and observe the tolerability and effects of morning draughts of oxcarbazepine." (PMID 31722684, 2019). "Next‐generation sequencing was used to determine the chromosomal deletion sites in patients with PRRT2 copy number variants, and to exclude mutations in other known causative genes for paroxysmal kinesigenic dyskinesia." (PMID 30307717, 2018). "This protein is poorly characterised, although recently a link between PRRT2 mutations and a rare neurological disease, paroxysmal kinesigenic dyskinesia, was established." (PMID 27907910, 2017). "We performed targeted deletion of Prrt2 (mutations in paroxysmal kinesigenic dyskinesia), and Arntl (a core component of the circadian clock) in the cynomolgus monkey (Macaca fascicularis)." (PMID 28585534, 2017). "Mutations in the PRRT2 gene were mainly associated with paroxysmal kinesigenic dyskinesia with a number of associated phenotypes including: (i) episodic ataxia; (ii) benign epilepsy; (iii) PED; and (iv) migraine and familial hemiplegic migraine." (PMID 26598494, 2015). "It is important to note that two clinically distinct disorders, benign infantile convulsion and paroxysmal kinesigenic dyskinesia, are allelic conditions caused by PRRT2 mutations." (PMID 24886244, 2014). "A PRRT2 missense mutation (c.981C > G, p.Ile327Met) was identified in two patients with benign infantile convulsion and three patients with paroxysmal kinesigenic dyskinesia as well as in two unaffected individuals." (PMID 24886244, 2014). "Mutations in proline-rich transmembrane protein 2 (PRRT2) are a cause of paroxysmal kinesigenic dyskinesia (PKD)." (PMID 25027704, 2014). "Identification of PRRT2 as the causative gene of benign infantile convulsion and paroxysmal kinesigenic dyskinesia allows genetic confirmation of the clinical diagnosis." (PMID 24886244, 2014). "Heterozygous PRRT2 gene mutations also cause paroxysmal kinesigenic dyskinesia in African-Americans." (PMID 22985072, 2012). "Recently, heterozygous mutations in PRRT2 (Chr 16p11.2) have been identified in Han Chinese, Japanese and Caucasians with paroxysmal kinesigenic dyskinesia." (PMID 22985072, 2012). "Other genes at 16p11.2 might modulate the effects of PRRT2 deficiency, as the frequency of paroxysmal kinesigenic dyskinesia in 16p11.2DS (<9%) appears to be much lower than its penetrance in PRRT2 mutation carriers (>60%)." (PMID 41235103, 2025). "In addition to BFIE, mutations in PRRT2 also cause paroxysmal kinesigenic dyskinesia (PKD), with a prevalence estimated at 1:150,000, characterized by recurrent episodes, transient chorea, dystonia, and/or ballismus." (PMID 37228410, 2023). "PRRT2 mutations account for a large fraction of cases of familial benign infantile epilepsy, paroxysmal kinesigenic dyskinesia (PKD) and PKD with infantile convulsions (PKD/IC) and, conversely, 95% of PRRT2 patients have a diagnosis within the benign familial infantile epilepsy PKD/IC-PKD spectrum." (PMID 36958475, 2023). "In this study, we uncover egress from the Golgi as an important step in the biology of IFITM3 by identifying the domain that regulates this process and that similarly controls the egress of the dispanins IFITM1 and PRRT2, protein linked to paroxysmal kinesigenic dyskinesia." (PMID 35396335, 2022). "In a cohort of Chinese families with members affected by paroxysmal kinesigenic dyskinesia, infantile convulsions, and choreoathetosis, direct sequencing showed three different pathogenic mutations (c.649dupC, c.776dupG, and c.649C → T) in the PRRT2 gene." (PMID 31801583, 2019).
paroxysmal kinesigenic dyskinesia (continued). "Mutations of the PRRT2 gene are the most common cause for paroxysmal kinesigenic dyskinesia." (PMID 30307717, 2018). "Paroxysmal kinesigenic dyskinesia (PKD), benign infantile epilepsy (BIE), and PKD with infantile convulsions (PKD/IC) are proline-rich transmembrane protein 2 (PRRT2)-associated paroxysmal disorders." (PMID 40861674, 2025). "PRRT2-related paroxysmal kinesigenic dyskinesia (PKD) typically presents with very brief, seconds-long attacks triggered by sudden voluntary movement or startle, and often responds dramatically to low-dose carbamazepine." (PMID 41568333, 2025). "Mutations in PRRT2 are associated with multiple childhood-onset neurological disorders, including BFIE [(OMIM) # 605751], paroxysmal kinesigenic dyskinesia [PKD; (OMIM) # 128200], and infantile convulsions and choreoathetosis [ICCA; (OMIM) # 602066]." (PMID 37228410, 2023). "Mutations in PRRT2 are associated with a variety of neurological disorders, such as BFIE, paroxysmal kinesigenic dyskinesia, and infantile convulsions and choreoathetosis, which account for more than 90% of all cases." (PMID 37228410, 2023). "Clinical phenotypes associated with PRRT2 gene mutations primarily include BIE, paroxysmal kinesigenic dyskinesia, and choreoathetosis." (PMID 38203422, 2023). "Genetic variation in PRRT2 is associated with benign familial seizures 2 (BFIS2, MIM# 605751) and episodic kinesigenic dyskinesia 1 (EKD1, MIM# 128200)." (PMID 36414972, 2022). "Mutations in proline-rich transmembrane protein 2 (PRRT2) result in conditions of involuntary movement, such as paroxysmal kinesigenic dyskinesia, benign familial infantile seizures, and episodic ataxia." (PMID 33112230, 2020). "Mutations in the proline-rich transmembrane protein 2 (PRRT2) are associated with paroxysmal kinesigenic dyskinesia (PKD) and several other paroxysmal neurological diseases, but the PRRT2 function and pathogenic mechanisms remain largely obscure." (PMID 29056747, 2018). "Paroxysmal kinesigenic dyskinesia (PKD) is an autosomal dominant disorder and PRRT2 is the causative gene of PKD." (PMID 25667652, 2015). "Previous studies reported that the proline-rich transmembrane protein 2 (PRRT2) gene was identified to be related to paroxysmal kinesigenic dyskinesia (PKD), infantile convulsions with PKD, PKD with migraine and benign familial infantile epilepsy (BFIE)." (PMID 25522171, 2014). "Mutations in the PRRT2 gene have been identified as the major cause of benign familial infantile epilepsy (BFIE), paroxysmal kinesigenic dyskinesia (PKD) and infantile convulsions with paroxysmal choreoathetosis/dyskinesias (ICCA)." (PMID 24370076, 2013). "It is also true, however, as in the case of PRRT2 paroxysmal kinesigenic dyskinesias, that having positive genetics allows us to go more safely towards a therapy such as carbamazepine or other sodium blockers, to strengthen the clinical suspicion of the referring physician." (PMID 40943684, 2025). "In addition to BFIS, PRRT2 mutations are also associated with paroxysmal kinesigenic dyskinesia (PKD) and infantile convulsions and paroxysmal choreoathetosis (ICCA), indicating a complex genotype-phenotype heterogeneity in PRRT2 mutations." (PMID 38406554, 2024). "Mutations in the proline-rich transmembrane protein 2 (PRRT2) gene cause a broad and heterogeneous spectrum of neurological diseases sharing a paroxysmal nature, such as paroxysmal kinesigenic dyskinesia, episodic ataxia, benign familial infantile seizures, and hemiplegic migraine." (PMID 36441479, 2023). "PRRT2 (Proline-rich Transmembrane protein 2) mutations underlie three major phenotypes: Benign Familial Infantile Epilepsy, Paroxysmal Kinesigenic Dyskinesia with or without infantile convulsions, and Infantile Convulsions with Choreoathetosis." (PMID 32899446, 2020).